SNORD88C (small nucleolar RNA, C/D box 88C)
Synonyms: HBII-180C
Gene: Small nucleolar RNA gene on chromosome 19 (50,802,328 to 50,802,418, reverse strand). Ensembl gene ENSG00000220988.
Gene Ontology:
Biological process: RNA processing
Cellular component: nucleolus
Homologues: Orthologues: chimpanzee SNORD88C (98% identical), macaque SNORD88C (97% identical), pig SNORD88C (96% identical), guinea pig SNORD88C (89% identical), dog SNORD88C (88% identical), mouse Gm26247 (82% identical), rat Snord88c (82% identical). Paralogues in human: SNORD88A (88% identical), SNORD88B (88% identical).
Diseases named in the same sentence as SNORD88C in open-access papers:
SNORD88C is named in the same sentence as 4 diseases in open-access papers, as found by Europe PMC text mining. Sharing a sentence is not in itself a finding about the gene and the disease. The quoted sentences say what the papers report.
non-small cell lung carcinoma (2 papers, 2024). A group of at least three distinct histological types of lung cancer, including non-small cell squamous cell carcinoma, adenocarcinoma, and large cell carcinoma. "SNORD88C acts as a non-invasive diagnostic biomarker for non-small cell lung cancer (NSCLC), promoting cancer progression by enhancing SCD1 translation through specific RNA modifications, which leads to inhibited autophagy and increased tumour growth and metastasis." (PMID 39107713, 2024). "For example, SNORD88C, up-regulated in tissue and plasma of non-small cell lung cancer (NSCLC), served as the circulating biomarker and guided 2’-O-methylation of 28 S rRNA then to regulate SCD1 translation and promote growth and metastasis." (PMID 38167096, 2024).
glioma (1 paper, 2023). A benign or malignant brain and spinal cord tumor that arises from glial cells (astrocytes, oligodendrocytes, ependymal cells). "The results demonstrated that knockdown of SNORD88C exhibited a significant decrease in the activity of pathways associated with rRNA, tRNA and mRNA, suggesting that SNORD88C is closely related to RNA metabolism and exerts a biological function in gliomas through the regulation of RNA levels." (PMID 38022536, 2023). "From the results of bioinformatics analysis, we inferred that SNORD88C has a major role in the development of glioma, and then performed in vitro experiments to validate it." (PMID 38022536, 2023). "RNA-seq results indicate that SNORD88C is involved in DNA replication, DNA methylation, DNA damage repair and regulation of gene expression levels in gliomas, and especially has a significant effect on RNA-related pathways." (PMID 38022536, 2023). "Transwell assay showed that overexpression of SNORD88C increased the invasive and migratory capacity of glioma cells." (PMID 38022536, 2023). "In addition, bioinformatics analysis suggested that SNORD88C functions as an oncogenic gene in glioma, which was validated by cellular phenotype experiments." (PMID 38022536, 2023). "In addition, SNORD88C could promote the proliferation, migration and invasion of glioma cells and is involved in a variety of biological processes related to DNA and RNA." (PMID 38022536, 2023).
SNORD88C also shares sentences with these, for which no sentence is quoted: cancer (1 paper); tumour (1).